INS (insulin)
Diseases named in the same sentence as INS in open-access papers (continued):
Sharing a sentence is not in itself a finding about the gene and the disease.
Insulin resistance (continued). "Since hepatic steatosis is increasingly recognized as a major contributor to systemic insulin resistance, this action may have played a significant role in improving systemic glucose homeostasis and insulin sensitivity." (PMID 23781256, 2013). "In the liver, insulin resistance is manifested by glucose overproduction during the basal state despite fasting hyperinsulinemia, combined with impaired hepatic response to the normal elevation in postprandial insulin." (PMID 23256660, 2013). "Interestingly, recent studies have shown that the knockdown of Mapk9 leads to reduced serum levels of glucose, insulin, and homeostatic model assessment and therefore reverses insulin resistance in HFD-fed mice." (PMID 23555558, 2013). "There is evidence in animal model of fat-induced insulin resistance supporting the idea that decreased insulin clearance may serve as a compensatory mechanism to alleviate β-cell stress from excessive demand." (PMID 24194886, 2013). "Indeed, it has been shown that hepatic protein kinase C (PKC) isoforms are involved in hepatocyte insulin resistance by inhibiting insulin signaling in human liver biopsy samples." (PMID 24264040, 2013). "The major mechanisms are hypothesized to be the stimulation of insulin secretion and increased insulin sensitivity by ameliorating insulin resistance via increased PPAR-γ activity." (PMID 23737828, 2013). "With beta cell dysfunction, insulin secretion is impaired whereas with insulin resistance, insulin may still be secreted but insulin insensitivity manifests in target tissues." (PMID 23542897, 2013). "In pathogenesis, this linkage might be explained by the insulin resistance(IR) mechanisms in the development of MetS, because insulin and insulin growth factors I and II supporting erythropoiesis in both vitro and vivo had been detected in laboratory studies." (PMID 24144016, 2013). "Under T2D condition, β-cells produce more insulin to compensate for insulin resistance." (PMID 24367624, 2013). "Insulin resistance and β cell function are inversely correlated with thyroid stimulating hormone which may be explained by insulin-antagonistic effects of thyroid hormones along with an increase in TSH." (PMID 23671867, 2013). "While two studies found an association between breastfeeding and markers of insulin resistance in overweight and obese children and adults, others did not see an association between breastfeeding and insulin sensitivity at ages 9–15 or 45–59 years." (PMID 24236134, 2013). "Here, we hypothesize that PEDF might be down regulated by insulin and then lead to the improved insulin resistance in type 2 diabetic patients during insulin therapy." (PMID 24367624, 2013). "However, if insulin resistance is present, normal insulin signaling would be impaired in hepatocytes leading to failure to suppress Sepp1 expression as well as that of gluconeogenic enzymes." (PMID 23760059, 2013). "Furthermore, the insulin resistance was evaluated by the homeostasis model assessment of insulin resistance (HOMA-IR) method : HOMA-IR = [fasting insulin (μU/mL) × fasting glucose (mmol/L)]/22.5." (PMID 24317433, 2013). "The high insulin values were most likely indicative of some degree of insulin resistance." (PMID 24156623, 2013). "Hyperglycaemia develops with increased insulin resistance and failure of insulin secretion." (PMID 23822206, 2013). "Interestingly 61% of women operated for breast cancer (cases) with HOMA-IR ≥ 2.5 presented subclinical insulin resistance with fasting plasma glucose levels and fasting plasma insulin levels in the normal range." (PMID 23497533, 2013). "Furthermore, insulin resistance impairs the ability of insulin to decrease pressure augmentation and CASP." (PMID 23978271, 2013).
Insulin resistance (continued). "ScN/Tie2-GFP mice, which lack a functional toll-like receptor 4 (TLR4), display lower fasting glucose and insulin levels and improved glucose tolerance compared to Tie2-GFP mice, suggesting that TLR4 deficiency decreases susceptibility to the development of insulin resistance." (PMID 23840960, 2013). "Moreover, FFAs were also revealed to have induced insulin resistance by initially disrupting the phosphorylation process in the insulin-signalling pathway and consequently reducing glucose oxidation and glycogen synthesis." (PMID 24324517, 2013). "Both PIs and NRTIs have also been associated with insulin resistance, through inhibition of muscular and adipocyte GLUT4 (insulin-regulated transmembrane glucose transporter), resulting in decrease glucose intake mediated by insulin in these tissues." (PMID 23782481, 2013). "We focused our analysis on PMNC because of the considerable evidence indicating that these inflammatory cells infiltrate insulin-sensitive tissues (skeletal muscle, adipocytes, and liver) where they promote insulin resistance and are also involved in the pathophysiology of AVD." (PMID 23671849, 2013). "GDM is associated with the development of inflammation, where adipose tissues play an important role in the regulation of insulin sensitivity by secreting adipokines which are involved in the pathogenesis pregnancy-induced insulin resistance, in the case obese pregnancies." (PMID 23805905, 2013). "In addition, the old rats developed insulin resistance with impairment in the liver insulin signaling compared with the young rats." (PMID 23442260, 2013). "The postweaning fasts are characterized by increased plasma free fatty acids (FFA), elevated plasma glucose, and decreased cellular insulin signaling activity, which collectively would constitute an insulin resistance phenotype." (PMID 23997935, 2013). "Interestingly, leptin was also significantly related with high concentrations of fasting glucose (r = 0.5227) and insulin (r = 0.2229), as well as elevated levels of insulin resistance (r = 0.3611) and circulating triglyceride (r = 0.4135)." (PMID 23986664, 2013). "Although significantly associated with direct measures of insulin resistance, HOMA-IR might have misclassified insulin sensitivity status." (PMID 23341938, 2013). "Perhaps, this is not surprising since PEG30-FGF21 Q108 at this dose (0.25 mg/kg) was recently reported to have beneficial effects in terms of normalizing insulin-stimulated glucose uptake in a diet-induced mouse model of insulin-resistance after acute treatment." (PMID 24039848, 2013). "Abnormal glycemic responses following an oral glucose challenge could be due to insulin resistance or impaired insulin secretion." (PMID 23607267, 2013). "Therefore, the effect of insulin resistance and the concomitant action of exogenous insulin is difficult to examine in these investigations." (PMID 24133491, 2013). "Indeed, adipocytokines are major regulators of hepatic insulin sensitivity potentially linking insulin resistance and obesity." (PMID 23762871, 2013). "Mass of visceral fat was highly correlated with insulin secretion and insulin resistance." (PMID 23061769, 2013). "Moreover, GSPE treatment in male rats treated with 25 mg/kg of GSPE for 21 days improves the insulin resistance state and counteracts the cafeteria-induced effects on insulin synthesis." (PMID 26904613, 2013). "Associations between normal weight obesity defined as the sum of the triceps and subscapular skinfolds >90th percentile with metabolic syndrome and its components and insulin resistance, insulin sensitivity and β cell function, 1978/79 Ribeirão Preto birth cohort." (PMID 23556000, 2013). "This protection from lipid-induced hepatic insulin resistance could be attributed to improvements in hepatic insulin signaling, as assessed by Akt phosphorylation at Ser473." (PMID 23175050, 2013).
Insulin resistance (continued). "Our results showed BM-contained diets could reduce HFD-induced body weight gain and related adipose tissue hyperplasia, improve insulin resistance and glucose intolerance, and lower serum levels of insulin and leptin." (PMID 24358329, 2013). "In addition, metformin increases the affinity of insulin for the insulin receptor, which reduces insulin resistance." (PMID 23983688, 2013). "In addition, compared to controls, the HIV-infected patients were characterized by peripheral insulin resistance as whole-body insulin-stimulated glucose uptake (Rd) and incremental glucose uptake (Rd basal – Rd clamp) were decreased." (PMID 23533568, 2013). "GH-induced insulin resistance may be developed by the increased FFA mobilization from adipose tissue which can then affects liver insulin sensitivity, and lead to insulin resistance and up-regulation of the PEPCK and G6Pase." (PMID 23761784, 2013). "Insulin resistance is characterized by the decreased ability of insulin to stimulate the use of glucose by muscles and adipose tissue leading to increased production of pancreatic insulin." (PMID 23782481, 2013). "A major factor separating the pathology of IGT and T2D is that the former displays high insulin levels to compensate insulin resistance, whereas at least in advanced T2D β-cell function and hence insulin levels are reduced while blood glucose and triglycerides are increased." (PMID 23401789, 2013). "Inflammatory mediators such as TNF-α and IL-6 either alone or through synergistic effect could lead to the development of insulin resistance by blocking the signal transduction of insulin, impairing insulin sensitivity, and increasing free fatty acids." (PMID 23840093, 2013). "This may explain why E2-treated mice have suppressed hyperglucagonaemia and lower insulin concentrations, as a decrease in hyperglucagonaemia improves glucagon-induced hepatic insulin resistance." (PMID 23132340, 2013). "In addition, PPAR-γ affects insulin sensitivity by regulating adipocyte hormones, cytokines, and proteins that are involved in insulin resistance." (PMID 23781121, 2013). "Following our in vitro observations, we sought to determine whether inhibition of PP2A would enhance hepatic insulin signaling in vivo in a model of hepatic insulin resistance." (PMID 24150286, 2013). "These conditions are known to induce insulin signalling pathway defect and insulin resistance." (PMID 24244361, 2013). "Insulin resistance, a state in which the response to insulin is blunted, may be initiated in multiple tissues, including white adipose tissue (WAT)." (PMID 23221991, 2013). "Thus, visceral adiposity is a stronger correlate of insulin resistance than subcutaneous adiposity and the improvements in insulin sensitivity after lifestyle interventions are mainly driven by the reduction in visceral adiposity." (PMID 23951064, 2013). "Moreover, our previous study indicated that in cultured human HepG2 hepatocytes, TNF-α induced insulin-resistance, as assessed by their decreased capacity to accumulate glycogen in the presence of insulin." (PMID 23437347, 2013). "A number of studies conducted in NAFLD patients have shown both an impaired ability of insulin to suppress endogenous glucose production, indicating the presence of hepatic insulin resistance, and an approximately 50% reduction in glucose disposal, a measure of whole-body insulin sensitivity." (PMID 24264040, 2013). "Several studies have reported that visceral adipocytes are less responsive than subcutaneous fat cells to the antilipolytic effect of insulin and that exposure of the liver to high concentrations of free fatty acids can induce changes in insulin signaling that promote hepatic insulin resistance." (PMID 24330822, 2013). "In liver, GH has a stimulatory effect on glucose production which may be a result of its antagonism of insulin action leading to hepatic/systemic insulin resistance." (PMID 23761784, 2013).
Insulin resistance (continued). "The thiazolidinediones represent a unique class of drug that may directly decrease insulin resistance by enhancing insulin action in skeletal muscle, liver, and adipose tissue." (PMID 23983807, 2013). "The JZD could reduce ERS and improve insulin signal transduction and insulin resistance in T2DM rats’ hippocampus and as a result improved the cognitive function." (PMID 23829668, 2013). "However, there are also ethnic differences in the level of insulin resistance, with black South African women and African American women being more insulin resistant than their white counterparts, even when matched for age and BMI." (PMID 23401754, 2013). "Additionally, insulin resistance involves an abnormal biological response of the body systems with regard to physiological levels of insulin, and this pathological feature of the disease is the key to the metabolic syndrome." (PMID 24324517, 2013). "Thus, in this animal model of obesity and insulin resistance, P1736 improved both hyperinsulinemia and muscle insulin sensitivity while lowering plasma glucose levels." (PMID 24194903, 2013). "It has been suggested that decreased insulin clearance may be a compensatory mechanism to lessen the demand on β-cells in an animal model of insulin resistance induced by high fat diet." (PMID 24194886, 2013). "All surrogates indexes correlate reasonably well with insulin sensitivity measured by euglycemic-hyperinsulinemic clamp, although they differentially reflect the contribution of individual organs, e.g., liver and muscle, to insulin resistance." (PMID 23326550, 2013). "Effects of pioglitazone on plasma glucose and insulin in fructose-drinking insulin resistance rats." (PMID 23527159, 2013). "Furthermore, Rimonabant corrected the insulin resistance and lowered plasma leptin, insulin and free fatty acid levels." (PMID 23712280, 2013). "Results suggest that fasting induces adipose-specific insulin resistance in elephant seal pups, while maintaining skeletal muscle insulin sensitivity, and therefore suggests that the onset of insulin resistance in fasting mammals is an evolved response to cope with prolonged food deprivation." (PMID 23997935, 2013). "Increased FPG is predominately induced by liver insulin resistance and a defect in the early phase of insulin secretion, whereas increased HbA1c is dominated by a combination of hepatic insulin resistance, muscle insulin resistance and impaired insulin secretion." (PMID 24188743, 2013). "This study was the first to show that exendin-4 could improve insulin sensitivity in an environment of insulin resistance, partly due to reductions in food intake and partly independent of changes in body weight and ambient glycemia." (PMID 23256660, 2013). "The increase in insulin requirement driven by insulin resistance may play a contributory role in the deterioration of β-cell function." (PMID 23886319, 2013). "Furthermore, the lower score of homeostasis model-assessment of insulin resistance (HOMA-IR) indicated that GHRH-KO mice had enhanced insulin sensitivity." (PMID 24175087, 2013). "Although the exact mechanism of abnormal insulin function is unknown, there is increasing evidence that plasma FFAs may act to induce insulin resistance." (PMID 24098655, 2013). "Although the mechanisms for the beneficial effects of regular exercise training alone have not been fully understood, improved insulin sensitivity and glucose uptake induced by muscle contraction after exercise training seem to play an important role in alleviating insulin resistance." (PMID 24454364, 2013). "Thus, both local/circulating GPCR ligands associated with insulin resistance/hyperinsulinaemia, and insulin itself, contribute to the high GRK2 levels observed in insulin-resistant rodent/human tissues." (PMID 24265619, 2013). "Besides liver, adipocytes also have a function in insulin resistance: iron treatment increased lipolysis and impaired glucose uptake in response to insulin." (PMID 23783556, 2013).
Insulin resistance (continued). "In addition, clinical examinations usually use the serum or urine C-peptide level to evaluate insulin resistance and as a surrogate marker of endogenous insulin secretion." (PMID 24358252, 2013). "Exogenous insulin administration and insulin resistance was reported to be significantly correlated with sympathetic overactivity and may increase sympathetic activity." (PMID 23383010, 2013). "Vascular ETD may precede insulin resistance, induce a reduction in insulin sensitivity, and produce a malignant cycle." (PMID 24499567, 2013). "Therefore, the presence of adipose insulin resistance and a whole-body insulin resistance-like phenotype, while muscle insulin sensitivity is maintained in late-fasted seals is unique among mammals." (PMID 23997935, 2013). "TNF-α is a critical mediator in insulin resistance induction, inhibition of which by phytol could convey the improvement of insulin sensitivity along with glucose disposal." (PMID 23300941, 2013). "AETPB treatment showed reduction of HbA1c and improvement in Hb levels, and it might be due to blood glucose lowering effect of AETPB possibly through reversal of insulin resistance or increasing insulin secretion by regeneration of pancreatic β-cells." (PMID 23936668, 2013). "Improvements in insulin resistance were further confirmed by insulin tolerance test." (PMID 23637966, 2013). "Finally, in a cohort of obese individuals classified as insulin resistant (homeostasis model assessment of insulin resistance (HOMA-IR) >2.5) and insulin sensitive, BAI and BMI differed in their correlations with cardiometabolic risk factors." (PMID 23776578, 2013). "The study showed that the expression of alpha-ketobutyrate served as early indicator in insulin resistance by differentiating the group of normal glucose tolerance-insulin sensitivity (NGT-IS) from normal glucose tolerance-insulin resistance (NGT-IR) among nondiabetic population." (PMID 24282409, 2013). "Since evidence showed PEDF was positive related with insulin resistance, we hypothesize that insulin treatment may down-regulate PEDF expression and then lead to the improved insulin sensitivity." (PMID 24367624, 2013). "In our previous study, an insulin tolerance test showed an increased high-fructose diet-induced insulin resistance; further, fasting blood glucose and insulin levels were significantly higher in the high-fructose group compared to the high-fat group in the current study." (PMID 24321741, 2013). "However, decreased insulin sensitivity (IS), that is, insulin resistance, was observed both in ATI and LI, which was frequently accompanied with compensatory hyperinsulinemia in T2D patients as well as in nondiabetics." (PMID 23843789, 2013). "Although it is difficult to ascertain whether defects in mitochondria occur before or after the onset of insulin resistance, it has been demonstrated that induction of mitochondrial superoxide production results in insulin resistant adipocytes." (PMID 24138787, 2013). "The next step to determining whether TNFα is key to insulin resistance is to evaluate whether TNFα can regulate other factors involved in impaired insulin signaling." (PMID 23592917, 2013). "Insulin-resistance stimulates pancreatic β-cells hyperplasia, in order to compensate for decreased hormone sensitivity; initial insulin overproduction is then followed by β-cell death and decreased insulin secretion." (PMID 23698776, 2013). "Indeed in insulin-resistant individuals, MCRI has been shown to be decreased, suggesting that changes in insulin resistance can independently impact insulin clearance." (PMID 23886319, 2013). "Since vaspin can improve glucose tolerance and insulin sensitivity, the increase in plasma vaspin levels may be a result of compensatory response to insulin resistance." (PMID 23772224, 2013).